BTF3 (basic transcription factor 3)
Diseases named in the same sentence as BTF3 in open-access papers (continued):
Sharing a sentence is not in itself a finding about the gene and the disease.
hepatocellular carcinoma (1 paper, 2024). A malignant tumor that arises from hepatocytes. "Our study found that BTF3 expression was upregulated in hepatocellular carcinoma tissues, and its high expression was associated with poor prognosis." (PMID 39707202, 2024). "First, EDU assay showed that the proportion of proliferative cells in BTF3 knockdown hepatocellular carcinoma cells was significantly reduced." (PMID 39707202, 2024). "In the current study, we first observed the expression level and prognosis of BTF3 in hepatocellular carcinoma tissues, and the results showed that BTF3 was highly expressed in hepatocellular carcinoma tissues and correlated with the prognosis of patients." (PMID 39707202, 2024). "In conclusion, our work identified the oncogenic role of BTF3 as an oncogenic transcription factor in hepatocellular carcinoma." (PMID 39707202, 2024). "Meanwhile, correlation analysis revealed that the expression of PDCD2L was highly correlated with that of BTF3 in 29 pairs of hepatocellular carcinoma tissues, which indirectly indicated the regulatory relationship between BTF3 and PDCD2L." (PMID 39707202, 2024). "BTF3, as an oncogenic transcription factor, is involved in various cellular processes in prostate, colorectal, esophageal, breast, and hepatocellular carcinomas, including DNA damage repair, cell stemness, proliferation, invasion, migration, and glycolysis." (PMID 39707202, 2024). "To clarify the mechanism of BTF3 as a transcription factor in hepatocellular carcinoma, we then utilized the chip-seq data and transcriptome data to identify potential targets of BTF3 and finally focused on the PDCD2L molecule." (PMID 39707202, 2024). "Meanwhile, we extracted proteins from 10 pairs of hepatocellular carcinoma tissues for western blot experiments, among which seven pairs of tissues showed significantly high expression of BTF3 in cancerous tissues." (PMID 39707202, 2024). "At the same time, overexpression of BTF3 promoted the proliferation of hepatocellular carcinoma cells." (PMID 39707202, 2024). "Knockdown of BTF3 significantly inhibited proliferation and promoted apoptosis of hepatocellular carcinoma cells by cell function assay." (PMID 39707202, 2024). "In the current study, we investigated the biological role of BTF3 in hepatocellular carcinoma and confirmed that PDCD2L is a downstream target of BTF3 as a transcription factor." (PMID 39707202, 2024). "Subsequently, we extracted mRNA from 29 pairs of hepatocellular carcinoma tissues for qRT-PCR, and the results showed that the expression of BTF3 in hepatocellular carcinoma tissues was significantly higher than that in paired paracellular carcinoma tissues." (PMID 39707202, 2024). "The mechanism of oncogenesis of BTF3 as a transcription factor in hepatocellular carcinoma is still unclear." (PMID 39707202, 2024). "Subsequently, we obtained that BTF3 promoted the proliferation and inhibited the apoptosis of hepatocellular carcinoma cells through the overexpression of BTF3 in hepatocellular carcinoma cells." (PMID 39707202, 2024). "Meanwhile, we provide reliable evidence for the potential application of BTF3 and PDCD2L as diagnostic and prognostic biomarkers and therapeutic targets in hepatocellular carcinoma." (PMID 39707202, 2024). "We found that knockdown of BTF3 significantly inhibited the proliferation of hepatocellular carcinoma cells, and overexpression of BTF3 promoted the proliferation of hepatocellular carcinoma cells by CCK8 assay." (PMID 39707202, 2024). "At the same time, overexpression of PDCD2L promoted the activity of hepatocellular carcinoma cells while knockdown of BTF3 could partially reverse this trend." (PMID 39707202, 2024). "The mechanism of BTF3 oncogenesis as a transcription factor in hepatocellular carcinoma is still unknown." (PMID 39707202, 2024). "Meanwhile, knockdown of PDCD2L promoted apoptosis in hepatocellular carcinoma cells as detected by flow cytometry, and this could be rescued by BTF3 overexpression." (PMID 39707202, 2024).
hepatocellular carcinoma (continued). "Recent studies have shown that BTF3 can promote glycolysis in hepatocellular carcinoma cells." (PMID 39707202, 2024). "In addition, flow cytometric analysis showed that the apoptosis rate of hepatocellular carcinoma cells with BTF3 knockdown was significantly increased." (PMID 39707202, 2024). "All these data indicate the oncogenic role of BTF3 in hepatocellular carcinoma cells." (PMID 39707202, 2024). "In conclusion, these data suggest that BTF3 is highly expressed in hepatocellular carcinoma tissues and is significantly correlated with a worse prognosis in patients with HCC." (PMID 39707202, 2024). "However, given the transcriptional activity of BTF3, the mechanism by which BTF3 regulates hepatocellular carcinoma development remains unclear." (PMID 39707202, 2024). "In this study, we identified a novel role of BTF3 in hepatocellular carcinoma through transcriptional up-regulation of PDCD2L involved in the proliferation and apoptosis of hepatocellular carcinoma cells." (PMID 39707202, 2024). "Our work shows that BTF3 can directly act on the promoter of PDCD2L to promote the transcription of PDCD2L and exert oncogenic effects in hepatocellular carcinoma." (PMID 39707202, 2024). "To investigate the potential function of BTF3 in hepatocellular carcinoma cells, we transfected MHCC97H and Huh7 cells with knockdown/overexpression plasmids of BTF3 and verified the changes of BTF3 expression in both cells by qRT-PCR." (PMID 39707202, 2024). "In addition, we also analyzed BTF3 expression in 89 pairs of HCC tissues using immunohistochemistry, and the results were consistent with the trend of PCR in 29 pairs of hepatocellular carcinoma tissues." (PMID 39707202, 2024). "To confirm the relationship between BTF3 and PDCD2L, we first observed the expression level of PDCD2L in hepatocellular carcinoma cells knocking down and overexpressing BTF3, and the results showed that the expression of PDCD2L was in the same trend of change as that of BTF3." (PMID 39707202, 2024).
liver cancer (1 paper, 2024). An epithelial or non-epithelial malignant neoplasm that arises from the liver. "It has been found that the expression of BTF3 is increased in a variety of cancers, including prostate, gastric, breast, pancreatic, colorectal, and liver cancers." (PMID 39707202, 2024).
lung carcinoma (1 paper, 2017).
prostate (1 paper, 2021). "However, the mechanisms underlying the role of BTF3 as an oncogenic transcription factor in prostate tumorigenesis have not been explored." (PMID 33414468, 2021).
prostate tumor (1 paper, 2021). "We also conducted immunohistochemical staining of BTF3 protein in a panel of primary human prostate tumor samples with adjacent non-cancerous tissues." (PMID 33414468, 2021). "Importantly, doxycycline-induced BTF3 knockdown significantly attenuated the growth of DU145-derived xenografts, validating the oncogenic role of BTF3 in prostate tumor development." (PMID 33414468, 2021).
rectal tumors (1 paper, 2019). "In the in vivo experiments, BTF3-siRNA inhibited the growth of rectal tumors, and in the microarray, we confirmed that BTF3 regulated the cell cycle related gene (MAD2L2, MCM3, and PLK1)." (PMID 31263147, 2019).
triple-negative breast carcinoma (1 paper, 2022). An invasive breast carcinoma which is negative for expression of estrogen receptor (ER), progesterone receptor (PR), and human epidermal growth factor receptor 2 (HER2). "Also, another study showed that basic transcription factor 3 (BTF3), a transcription initiation factor in RNA pol II promoted the stemness and suppressed the interferon regulatory factor 7 (IRF7) in triple-negative breast cancer." (PMID 36550571, 2022).
cancer (18 papers, 2012 to 2025). A tumor composed of atypical neoplastic, often pleomorphic cells that invade other tissues. "Increasing evidence has shown that, as a transcription factor, BTF3 is associated with the development of several types of cancers." (PMID 31263147, 2019). "Cancer stem-like characteristics in PCa including self-renewal and metastatic potential were impaired by BTF3 loss and promoted by BTF3 overexpression." (PMID 31138311, 2019). "In more recent studies, BTF3 upregulation has been correlated with tumor prognosis and the transcriptional activity of BTF3 has been implicated in proliferation and cancer progression." (PMID 30242148, 2018). "BTF3 has been reported to be highly linked with many cancers." (PMID 38203709, 2023). "Basic transcription factor 3 (BTF3) is associated with the development of several cancers." (PMID 31263147, 2019). "Here, we provide evidence that three components associated with embryonic and cancer cell biology are part of a common pathway, an adhesion molecule (N-cadherin), fragments of another adhesion molecule (Cx43) and a transcription factor (BTF3)." (PMID 30242148, 2018). "Thus, BTF3, a transcription factor previously associated with gene expression in cancer systems, regulates embryonic gene expression in neural crest, a cell population that has been likened to cancer cells." (PMID 30242148, 2018). "A decrease in BTF3 by resveratrol, which controls cancer-associated gene transcription, could be pursued for inhibiting cell proliferation of adenocarcinoma of the esophagus, leading to the apoptosis of these cells, as seen in the molecular analysis in the present study." (PMID 34830970, 2021). "Transcription factors, such as BTF3, play a central role in controlling the gene expression of cancer genes." (PMID 34830970, 2021). "Although two distinct functional mechanisms of BTF3 in different cancer types have been reported, its role in CRC is still unclear." (PMID 33644029, 2020). "As a transcription factor, BTF3 has been proven to regulate gene expression by binding DNA elements in cancer." (PMID 33644029, 2020). "Basic transcription factor 3(BTF3) is involved in the apoptotic process of various cells and exhibits over-expression in malignant tumors." (PMID 31480213, 2019). "Among the top scoring gene sets in high-BTF3 (P < 0.05, FDR < 0.1), we found several gene sets associated with cancer onset and progression." (PMID 31138311, 2019). "Many molecules are involved in regulating BTF3 in the progression of various cancers." (PMID 39707202, 2024). "Interestingly, two distinct roles of BTF3 in cancer have been reported." (PMID 33644029, 2020). "Other signaling proteins involved in transcriptional control include basic transcription factor 3 (BTF3) and breast cancer anti-estrogen resistance 1 (BCAR1) protein, which are downregulated upon Gal4 expression." (PMID 35742860, 2022). "As a decreased binding peak of BTF3 was located in the promoter region of CHD1L and CHD1L has been reported as an oncogene in CRC and other cancer types, we chose CHD1L as a target candidate." (PMID 33644029, 2020). "However, the mechanisms of BTF3 in cancer progression remain unclear." (PMID 31138311, 2019). "We determined that EPHB2 has significant interactions with several key proteins, including L1CAM, ABL2, KDM4A, BTF3, and SRC, suggesting that it may form a functional network critical to cancer progression." (PMID 41322437, 2025). "Moreover, BTF3 is overexpressed in cancer cells and promotes EMT, further driving cancer progression." (PMID 40754247, 2025). "Additional proteins with significant upregulated scores (BTF3, SNRPA, and NUTF2), which promote cancer in other types of malignances, also lead to lower survival probability in CLL patients, apart from BTF3 that seems to affect survival only during the initial days of disease development." (PMID 39202022, 2024).
cancer (continued). "Triple-labeled immunofluorescence (BTF3, HINT1 and NDRG1) in tissue array showed a significant (p<0.02) change in co-localization coefficients for BTF3 and NDRG1 co-expression in biochemical relapse vs non-relapse cancer epithelium." (PMID 24386364, 2013).
tumor (12 papers, 2018 to 2026). "BTF3 knockdown HT29 cells exhibited reduced tumor size (42.3%, p < 0.05, N = 6), compared to the control group." (PMID 33644029, 2020). "Next, to confirm further that BTF3-siRNA can suppress tumor growth, we established a xenograft model using a lentivirus-mediated siRNA therapy protocol." (PMID 31263147, 2019). "To test whether this change in the stem cell traits induced by BTF3 has consequences for the ability of PCa cells to proliferate and invade, we investigated the role of BTF3 on tumor growth using a xenograft model." (PMID 31138311, 2019). "Together, these experiments show that BTF3 inhibition mediated suppression of prostate stem-like phenotype which resulted in a block of tumor growth and progression, which may be utilized as a treatment strategy in patients." (PMID 31138311, 2019). "These SPP1+ macrophages enhanced tumor cell proliferation, stemness, and migration via CD44-Wnt-BTF3 signaling pathway." (PMID 41993204, 2026). "In contrast, patients with insufficient expression of SORBS2, PAM, ZFAT, DOCK7, ERMAP, BTF3, and GUSB in the tumor tissues had shorter survival duration than patients in the high-expression group." (PMID 37315301, 2023). "Finally, expression of BTF3 and CHD1L in tumor-infiltrating immune cells was further analyzed, and both genes showed significant correlation with CD8+ T cells, suggesting their potential role in CD8+ T cell regulation." (PMID 33644029, 2020). "Tumor weights in the negative group (0.72 ± 0.43 g) were significantly higher (P < 0.01) than in the BTF3-siRNA group (0.17 ± 0.23 g)." (PMID 31263147, 2019). "BTF3 expression level was not only significantly higher in CRC tissue than in ANCT tissue (2.61 ± 0.07 vs 1.90 ± 0.03, P < 0.001) but BTF3-siRNA decreased tumor formation in a nude mice model." (PMID 31263147, 2019). "Although, tumor weights in the negative group were inhibited compared with the blank control group (1.38 ± 0.59 g), the maximum inhibitory effect was induced by BTF3-siRNA." (PMID 31263147, 2019). "On day 16, tumor volumes in the control (1,745.34 ± 712.90 mm3) and negative control (954.93 ± 517.12 mm3) groups rapidly increased when compared to the BTF3-siRNA group (202.60 ± 297.64 mm3, P < 0.05)." (PMID 31263147, 2019). "The Gal4-dependent upregulation of PURB (transcriptional activator protein Pur-beta) and MAPKAPK3 (MAPK-Activated Protein Kinase 3) expression, as well as the downregulation of BTF3 (Basic Transcription Factor 3) and BCAR1(Breast Cancer Anti-Estrogen Resistance Protein 1), could be confirmed." (PMID 35742860, 2022).
infection (2 papers, 2014 to 2016). The state of being infected such as from the introduction of a foreign agent such as serum, vaccine, antigenic substance or organism. "Under phytoplasma infection, ACT1 and PAIP were identified as suitable reference genes by geNorm, whereas BTF3 and EF1γ were identified as suitable ones by NormFinder." (PMID 27116123, 2016).
BTF3 also shares sentences with these, for which no sentence is quoted: Breast (2 papers); Glioblastoma multiforme (2); keloid (2); adenocarcinoma (1); astrocytoma (1); cervical cancer (1); congenital heart defects (1); gastric adenocarcinoma (1); hypopharyngeal squamous cell carcinoma (1); lymph node metastasis (1); malignant brain tumor (1); osteosarcoma (1); rectal adenocarcinoma (1).